PTBP2 (polypyrimidine tract binding protein 2)
Diseases named in the same sentence as PTBP2 in open-access papers (continued):
Sharing a sentence is not in itself a finding about the gene and the disease.
tumor (26 papers, 2015 to 2026). "Bioinformatics analysis further suggests that the SOX4/PTBP2 axis is associated with the tumor immune microenvironment and the sensitivity to several anti-cancer drugs." (PMID 42255218, 2026). "Further functional studies verified that PTBP2 induced the chemotactic activity and repolarization of tumor-associated monocytes/Mφs in NB cells, thereby inhibiting tumor growth." (PMID 39594898, 2024). "Functional studies revealed that PTBP2 in NB cells induced the chemotactic activity and repolarization of tumor-associated monocytes and Mφs, which, in turn, inhibited NB growth and dissemination." (PMID 37040518, 2023). "Therefore, PTBP2 induced chemotaxis of tumour-associated monocytes and macrophages through the CCL5/CCR5 axis within the TME." (PMID 37887559, 2023). "We observed a significant decrease in the Q score of PTBP2, BNIP3, and Ki-67 in Ptbp2-KO-KCL22 compared to the KCL22-NTC tumor; however, overexpression of BNIP3 in the Ptbp2-KO-KCL22 cells showed a higher Q score." (PMID 40113750, 2025). "Our study underscores the role of PTBP2 in promoting cell proliferation and tumor formation while enhancing autophagy through Bnip3, thereby supporting the role of PTBP2 as an oncogene in CML." (PMID 40113750, 2025). "Ki67 staining of tumor sections indicated that knockingdown or overexpression of PTBP2 with human PBMCs promoted or suppressed the proliferation of tumor cells in mice, respectively." (PMID 37040518, 2023). "The differential levels of PTBP2 and IRF9 induced chemotaxis of tumour-associated monocytes and macrophages through chemokines and thereby limited NB growth." (PMID 37887559, 2023). "In contrast, the expression level of PTBP2 was lower in tumor tissues compared with that in normal tissues." (PMID 36203873, 2022). "MALAT1 can competitively bind to SFPQ leading to PTBP2 release from the SFPQ/PTBP2 complex, which enhances the function of PTBP2 in promoting tumor cell proliferation and migration." (PMID 34778078, 2021). "Moreover, PTBP2, rather PTBP1, in mediastinal NB with a favorable outcome was also found to be abundantly expressed on the basis of sequence data, hinting that PTBP2-mediated alternative splicing exerted a tumor-inhibiting effect in NB." (PMID 37040518, 2023). "In vivo bioluminescence imaging represented that PTBP2 overexpression markedly inhibited the metastatic tumor size, while depletion of PTBP2 expanded the metastatic tumor size exposed to human PBMC transplantation, while no obvious difference was observed among groups without human PBMCs." (PMID 37040518, 2023). "In particular, PTBP2 may be a tumor-inhibiting gene in both stage- and prognosis-dependent NB tumors." (PMID 37040518, 2023). "We further identified the alternative splicer PTBP2 from proteomic analysis of NBs with distinct prognoses and verified that monocytes and Mφs polarized by PTBP2-treated NB cells also act back to regulate tumor cell proliferation." (PMID 37040518, 2023). "However, CCL5 and anti-CCL5 antibodies rarely affect the tumor-inhibiting effect induced by PTBP2, leading us to hypothesize that PTBP2-attracted monocytes and Mφs may exert their main antitumor effects through other mediators." (PMID 37040518, 2023). "Overall, a complex interaction between NB tumour cells, namely, a cascade of regulatory and secreted factors, chemokines, and cytokines downstream of the tumour suppressor PTBP2, affected monocytes and macrophages, and this could lead to the limiting of NB growth within the TME." (PMID 37887559, 2023). "Another study found that MALAT1 promotes tumour growth and metastasis in CRC by competitively binding to SFPQ (also known as Polypyrimidine Tract-Binding Protein-associated splicing factor) and releasing oncogene PTBP2 (polypyrimidine tract binding protein 2) from the SFPQ/PTBP2 complex." (PMID 31430887, 2019). "Tumor weight and volume were higher in KCL22-NTC and Ptbp2-KO-Bnip3-OE-KCL22 cells than in Ptbp2-KO-KCL22 cells (respectively)." (PMID 40113750, 2025).
tumor (continued). "MALAT1, as a splicing factor proline-and glutamine-rich (SFPQ) bound competitor, will accelerate the dissociation of PTBP2 from the SFPQ/PTBP2 complex, enhance the function of PTBP2, and promote the proliferation and migration of tumor cells." (PMID 36829256, 2023). "MALAT1 has been observed that interacts with SFPQ, releases PTBP2 from the SFPQ/PTBP2 complex (SFPQ-detached PTBP2), and accelerates tumor growth and metastasis." (PMID 35305641, 2022). "We found strong positive correlations of PTBP1 with Th2 cells, PTBP2 with T helper cells and Tcm, and PTBP3 with T helper cells, Tcm, and Th2 cells in most tumor types." (PMID 36203873, 2022). "We first performed differentiation analysis and correlation analysis on the expression of the PTBP1, PTBP2, and PTBP3 genes in 30 tumor types using TCGA." (PMID 36203873, 2022). "We used the Cancer Genome Atlas (TCGA) to examine the expression levels of PTBP1, PTBP2, and PTBP3 in normal and tumor tissues, and cBioPortal was used to examine the genomic alterations." (PMID 36203873, 2022). "Among PTBPs, PTBP1 showed the highest RNA expression level in tumor tissues, followed by PTBP3; the expression level of PTBP2 was the lowest among the three genes." (PMID 36203873, 2022). "The mRNA expression level of PTBP2 in normal tissues was higher than PTC, and NOVA2 expression was significantly involved in tumor stage, high expression in I-II stages and low expression in III-IV stage for PTC." (PMID 34722250, 2021). "It has been reported that MALAT1 overexpression enhances cell proliferation and migration in vitro, and promotes tumor growth and metastasis in nude mice, due to tumor suppressor gene SFPQ and proto-oncogene PTBP2." (PMID 27888635, 2017). "PTBP2-mediated induction of autophagy through BNIP3 may provide CML cells with extra nutrients and promote further tumor progression." (PMID 40113750, 2025). "Overall, our results show that the switch of monocytes to the inflammatory subset and IFN-I signaling activation by PTBP2-overexpressing NB cells, which were responsible for the tumor-inhibiting effect, was independent of the CCL5/CCR5 axis." (PMID 37040518, 2023). "We finally identified PTBP1 in ACC, KIRP, and LGG; PTBP2 in ACC and KICH; and PTBP3 in ACC, LGG, and PAAD as potential prognostic biomarkers that may be involved in tumor progression in these tumor types." (PMID 36203873, 2022). "Moreover, we observed that 21 splicing factor genes showed significantly differential AS between SS and tumor-adjacent tissues, such as HNRNPA1, PTBP2, QKI, RBFOX2, and TRA2A." (PMID 36118864, 2022). "Also, the interaction between PTBP2 and SFPQ regulated by MALAT‐1 RNA is known to promote tumor growth and metastasis." (PMID 34459124, 2021). "Regarding the underlying molecular mechanisms, MALAT1 showed the ability to competitively bind to the tumor suppressor gene SFPQ and release the proto-oncogene PTBP2 from the SFPQ/PTBP2 complex, while the increased SFPQ-detached PTBP2 could promote tumor growth and migration." (PMID 26307974, 2015). "However, neither CCL5- nor anti-CCL5-neutralizing antibody affected NB cell migration and clone abilities induced by the PTBP2-altered NB cell–monocyte system, indicating that the tumor-inhibiting effect of PTBP2-induced monocytes/Mφs was not determined by the CCL5/CCR5 axis." (PMID 37040518, 2023). "Furthermore, MALAT1 regulates proliferation, migration, and promotes tumor growth and metastasis in nude mice, this regulation could be through SFPQ and AKAP-9 as MALAT1 interact with SFPQ, hence releasing PTBP2 from the SFPQ/PTBP2 complex, facilitating cell proliferation and migration." (PMID 31632922, 2019).
cancer (16 papers, 2015 to 2026). A tumor composed of atypical neoplastic, often pleomorphic cells that invade other tissues. "Additionally, PTBP2 promotes autophagy by binding and stabilizing Bnip3, which has been implicated in cancer cell subpopulations and can be a potential therapeutic target." (PMID 40113750, 2025). "Indeed, a Ptbp2/Sfpq (Ptb-associated splicing factor) complex has been shown to be involved in cancer metastasis involving activation of β-catenin signaling." (PMID 32962040, 2020). "Both SLC25A30 and PTBP2 are described to influence mitochondrial function and promote cancer cell proliferation." (PMID 38604503, 2024). "Interestingly, when we analyzed the expression correlation of PTBPs, we found that PTBP1/3 appeared to have opposite expression trends to PTBP2 in pan-cancer." (PMID 36203873, 2022). "PTBP2 has been found highly expressed in cancer cells and can promote cancer cell proliferation." (PMID 32774415, 2020). "In cancer cells, MALAT1 can further disrupt the formation of a splicing modulator complex through hijacking the SFPQ factor (proline- and glutamine-rich SF; or PSF for PTB-associated SF), thereby inhibiting its interaction with the tumour growth factor PTBP2." (PMID 31698782, 2019). "Since PTBP1 is abundant in cancer cells we moved forward with studies focused on PTBP1 over PTBP2." (PMID 30568224, 2019). "SFPQ-released PTBP2 then promotes the proliferation of cancer cells." (PMID 31698782, 2019). "In addition, ELAVL1 and PTBP2 also participate in cancer progression via AS function." (PMID 33281863, 2020). "Spearman correlation analysis on the pan-cancer dataset from cBioPortal yielded 926 mRNAs co-expressed with PTBP1, 657 mRNAs co-expressed with PTBP2, and 874 mRNAs co-expressed with PTBP3 (|R| ≥ 0.4, p < 0.05)." (PMID 36203873, 2022). "Cancer cells take advantage of high levels of PTBP1 and PTBP2 to impair the inclusion of exon 4, thereby allowing the overexpression of full length SRSF3 and promoting cell proliferation and transformation." (PMID 26416554, 2015). "Primary OSCC cells and CAL 27 cancer cell line had higher level of PTBP1 and PTBP2 than normal cells." (PMID 26416554, 2015). "Thus, we investigated the expression, function, and immune characterization of PTBP1, PTBP2, and PTBP3 in pan-cancer." (PMID 36203873, 2022). "Remarkably, PTBP1 on Th2 cells, PTBP2 on T helper cells and Tcm, and PTBP3 on T helper cells, Tcm, and Th2 cells may have broad positive regulatory effects in pan-cancer." (PMID 36203873, 2022). "This study comprehensively and systematically analyzed the prognostic value, genetic variation, and signaling pathways of PTBP1, PTBP2, and PTBP3 and the correlation of PTBP expression with TILs, ICP, TMB, MSI, and drug sensitivity from a pan-cancer perspective." (PMID 36203873, 2022). "PTBP1, PTBP2 and PTBP3 may be potential biomarkers for prognosis and immunotherapy in pan-cancer and may be novel immunotherapeutic targets." (PMID 36203873, 2022). "The lack of PTBP2 along with elevated levels of PTBP1 in cancer led us to focus our efforts on PTBP1." (PMID 30568224, 2019). "Notably, when KCL22-NTC cells were subcutaneously injected into the flanks of mice, they gave rise to malignant tumors, unlike Ptbp2-KO-KCL22 cells." (PMID 40113750, 2025). "The immunohistochemistry (IHC) results showed that KHSRP, SRSF3 and RBM9 were located in nucleus, and the expression of SRSF3 and RBM9 were significantly lower in cancer than normal thyroid, while there was no significantly different between KHSRP, NOVA2 and PTBP2 in carcinoma and normal tissues." (PMID 34722250, 2021).
neurodevelopmental disorder (2 papers, 2021 to 2023). A behavioral and cognitive disorder with onset during the developmental period that involves impaired or aberrant development of intellectual, motor, or social functions. "Our data comprehensively map PTBP2-dependent alternative splicing in human neurons and cerebral cortex, guiding development of novel therapeutic tools to benefit neurodevelopmental disorders." (PMID 37149717, 2023). "Focusing on neurodevelopmental disorders, we cross-referenced this list of alternatively spliced, PTBP2-regulated transcripts with the Orphanet database of disease-causing genes." (PMID 37149717, 2023).
neurological disorders (2 papers, 2021 to 2023). "PTBP2 depletion drives differential expression of 304 genes associated with synaptic organization, function, and plasticity, and we identified concomitant AS and differential gene regulation of several genetic causes of neurological disorders." (PMID 37149717, 2023).
hematological malignancies (1 paper, 2022). "To date, PTBP2, TMEM51, and MTOR have been found as fusion partners of KAZN by RNA sequencing studies in solid tumors, while, as far as we know, rearrangements of KAZN have never been described in hematological malignancies." (PMID 34859285, 2022).
PTBP2 also shares sentences with these, for which no sentence is quoted: autism spectrum disorder (2 papers); neurodegenerative disease (2); non-small cell lung carcinoma (2); amyotrophic lateral sclerosis (1); anorexia nervosa (1); breast carcinoma (1); cervical cancer (1); colorectal (1); erythroleukemia (1); gallbladder cancer (1); infection (1); Infertility (1); laryngeal squamous cell carcinoma (1); leukemia (1); Nephroblastoma (1); osteosarcoma (1); ovarian carcinoma (1); pancreatic cancer (1); Parkinson disease (1); skeletal dysplasia (1); small cell lung carcinoma (1); soft tissue sarcoma (1).